TERT (telomerase reverse transcriptase)
Diseases named in the same sentence as TERT in open-access papers (continued):
Sharing a sentence is not in itself a finding about the gene and the disease.
melanoma (continued). "TERT promoter mutations are shown to be tightly associated with the presence of FGFR3 and BRAFV600E mutations in BC and PTC or melanoma, respectively." (PMID 27438857, 2016). "The data suggest that, at least in the investigated melanoma cell lines, TERT expression is dependent on the activation of the MAPK pathway in the presence of TERT promoter mutations." (PMID 27449293, 2016). "The somatic transitions C228T and C250T in the TERT promoter do not only occur in melanoma, but strikingly in numerous malignancies such as hepatocellular carcinoma (HCC) and are among the most frequent mutations in cancer." (PMID 26992833, 2016). "Immortalized LP/TERT melanocytes and two melanoma cell lines HMV-II and C32 were transfected with siRNA against NRF2 or control siRNA." (PMID 27045471, 2016). "The initial TERT promoter mutation discovery came from a causal A > C germ line mutation at –57 bp (from ATG start site; Chr 5:1,295,161 hg19 co-ordinate) in a large melanoma family." (PMID 27449293, 2016). "In melanoma the TERT promoter mutations occur together with BRAF and NRAS mutations more frequently than per chance, suggesting a link between TERT expression and MAPK pathway activation during immortalization of melanocytes via ETS proteins." (PMID 27449293, 2016). "Our study provides evidence of a direct link between TERT expression and MAPK pathway activation through the ETS1 transcription factor in melanoma cells carrying a TERT promoter mutation." (PMID 27449293, 2016). "Germline mutations in additional genes were recently associated with melanoma occurrence: MITF, BAP1, TERT promoter, POT1, and MGMT." (PMID 26106605, 2015). "Should these findings be validated in additional cohorts, they argue that compared to the much more frequent and prognostically relevant TERT promoter mutations, SDHD promoter mutations play a relatively minor role in melanoma." (PMID 26327518, 2015). "Variants in the TERT-CLPTM1L region, for example, have been associated with basal cell carcinoma, melanoma, and glioma, as well as lung, bladder, prostate, pancreatic, and cervical cancers." (PMID 25789475, 2015). "In contrast to the initial report and promoter mutations in the TERT gene, our analysis suggests that SDHD promoter mutations are a relatively rare event in melanoma (4% of tumors) of unclear clinical and prognostic relevance." (PMID 26327518, 2015). "Taken together, our findings provide further evidence of pleiotropic effects in opposite directions in the TERT-CLPTM1L region, where variants associated with increased risk for lung and other cancers are simultaneously associated with reduced melanoma risk." (PMID 25789475, 2015). "For population based melanoma, recent large scale genome wide association studies in melanoma and naevi have discovered new common low penetrance genes (MTAP, PLA2G6, TERT and IRF4 for example) associated with both naevi number and melanoma." (PMID 23796690, 2013). "Another SNP (rs4635969) in TERT-CLPTM1L, a region that was previously associated with multiple cancers including melanoma, showed a suggestive association with TL (P = 0.005)." (PMID 23990928, 2013). "One previous study assessed the relationship between genetic variants in five telomere genes and the risk of melanoma and found two single nucleotide polymorphisms (SNPs) in TERT and one in TRF1 to significantly increase the risk of melanoma." (PMID 23300679, 2012). "The level of TERT expression is increased for superficial spreading melanoma, which is believed to prevent the cells from entering apoptosis." (PMID 22649681, 2011). "When cells were infected with Ad-TERT-Apoptin viruses, the growth of melanoma cells (line A375 and B16) was suppressed, resulting in apoptosis, whereas the normal epidermal melanocytes were protected from this effect." (PMID 22649681, 2011).
melanoma (continued). "hTERTC27 contains two peptides, p973 and p988, both of which have been shown to induce TERT specific CTLs in vitro or in vivo to lyse TERT+ tumor cells, including melanoma B16 cells." (PMID 20856939, 2010). "For instance, TERT is required for melanoma progression, avoiding immune rejection and regression." (PMID 39858033, 2025). "Melanoma cells are predominantly TERT promoter mutant cancers and are typically RAS driven." (PMID 40560846, 2025). "On the other hand, germline mutations in CDK4 or in the DNA repair genes BAP1 (BRCA1 associated protein-1), APEX1 (apopurinic/apurinic-endodeoxyribonuclease 1) or even TERT-linked gene (TERT, POT1, ACD, TERF2IP) mutations may also predispose to melanoma." (PMID 40361349, 2025). "Melanomas harbouring TERT promoter mutations are associated with elevated TERT expression by RT-PCR, expressed as high TERT mRNA levels compared to melanomas without mutations." (PMID 40361989, 2025). "Increased TERT expression was observed in metastases from primary melanomas with a Breslow index under 2 mm and could contribute to early metastasis." (PMID 40361989, 2025). "We found a significant association between TERT protein expression and the patient’s age, the melanoma’s development on a preexisting nevus and the absence of a prior personal diagnosis of melanoma." (PMID 40361989, 2025). "Mutations in the TERT promoter are observed at high frequencies in tumors characterized by lower proliferative potential, including melanoma and HCC, but are infrequent or virtually absent in highly proliferative cancers, such as breast and testicular cancer." (PMID 39871386, 2025). "Moreover, the genetic analysis efficiency of LINC00518 and PRAME is significantly higher than that of TERT (TERT is commonly used as a marker to identify malignant melanoma)." (PMID 39108268, 2024). "The TERT-p mutation is not seen in most nevi, but likely occurs early in the evolution of melanomas." (PMID 38247727, 2024). "TERT may influence the local invasion of primary melanoma cells through its impact on cellular programs, such as NF-kB and metalloproteinases, beyond its canonical telomerase activity." (PMID 39078811, 2024). "Next-generation sequencing has made it possible to identify high-risk melanoma variants in genes related to cell cycle control, such as BAP1, and in genes related to the telomere maintenance pathway, such as TERT, and the protective complex genes POT1, TERF2IP, and ACD." (PMID 39335684, 2024). "BRAF/RAS mutations and TERT promoter mutations commonly coexist to form genetic duets that drive poor clinical outcomes of PTC and hence are the main players in current genetic-based risk management of PTC and some other cancers as well, such as melanoma." (PMID 38735658, 2024). "TERT is widely overexpressed in various cancers, including different subtypes of melanoma." (PMID 38695555, 2024). "Our finding of a relatively high percentage of TERT mutations in primary melanomas in this cohort may reflect the high-risk nature of these stage IIB and IIC melanomas." (PMID 38158497, 2024). "Our study suggests additional non-coding drivers beyond the well-characterised TERT promoter in melanoma, offering new insights into the disruption of complex regulatory networks by non-coding mutations that may contribute to melanoma development." (PMID 39367275, 2024).
melanoma (continued). "In addition, the presence of TERT promoter mutations is often associated with co-occurring mutations in BRAF or NRAS, indicating a synergistic effect on melanoma progression." (PMID 39200315, 2024). "In addition to BRAF, other genes have been found mutated in sporadic melanomas including NRAS, TERT, NF1, and KIT." (PMID 37627054, 2023). "Therefore, to better understand the connection between TERT expression and resistance to BRAF and MEK inhibitors, we conducted studies in BRAF-mutated melanoma cells." (PMID 37296851, 2023). "Similarly, a high frequency of TERT promoter aberrations is also found in NRAS mutant melanomas, making TERT activity inhibition a potential therapeutic target in this population." (PMID 37239381, 2023). "Importantly, such mutations drive the overexpression of TPP1-S, which in the presence of mutant TERT promoter and increased TERT levels lead to synergistic telomere lengthening and cooperate in the indefinite proliferation of melanoma cells." (PMID 38033865, 2023). "The local invasion of primary melanoma cells might be regulated through increased TERT expression affecting cellular programs, such as NF-kB or metalloproteinases in addition to canonical telomerase activity." (PMID 37418389, 2023). "The high prevalence of TERT promoter mutations was confirmed in most tumour types such as glioma, bladder cancer, oral cavity carcinoma as well as melanoma and non-melanoma skin cancers." (PMID 38033865, 2023). "The authors showed that the negative prognostic effect of the TERT promoter mutations in melanoma patients was only visible in patients who did not carry the rs2853669 SNP." (PMID 37296851, 2023). "In human melanoma cells, the inactivation of the p16 pathway (encoded by the CDKN2A gene) and mutations occurring in the telomerase reverse transcriptase (TERT) promoter may be required for the melanoma to successfully avoid senescence." (PMID 37174106, 2023). "Since melanoma metastases with high TERT expression were shown to have originated from thinner primary tumors, we conclude that upregulation of TERT expression may contribute to metastasis." (PMID 37418389, 2023). "On the other hand, G-361 is a BRAF/V600E and TERT mutant amelanocytic melanoma cell line." (PMID 38069171, 2023). "Subanalyses of the three tumor types with the highest prevalence of TERT alterations consistently showed a trend toward shorter survival for patients with altered TERT promoters in brain tumors, head, and neck cancers, and melanoma/skin tumors." (PMID 36979671, 2023). "Using multivariate models, we found no consistent association for TERT promoter mutations or TERT expression with the survival rate in melanoma cohorts under immune checkpoint inhibition." (PMID 37418389, 2023). "Genetic alterations in the TERT gene have been extensively studied in melanoma." (PMID 37504268, 2023). "In conclusion, our analyses did not support a significant association between TERT genetic alterations and survival in melanoma patients." (PMID 37418389, 2023). "Therefore, panel testing for POT1, TERF2IP, ACD, and TERT should be considered when familial melanoma cases exhibit spitzoid differentiation." (PMID 36876055, 2023). "In line with the proposed concept of a two-step activation of TERT, the up-regulation of TERT expression in later stages of melanoma development could aid the survival of melanoma cells in hypoxic tumors and metastasis to other sites." (PMID 37418389, 2023). "Spitzoid morphology involving at least 25% of the tumor was observed by at least 3 dermatopathologists in 77% (23 of 30), 75% (3 of 4), 50% (2 of 4), and 50% (1 of 2) of melanomas from individuals with germline variants in POT1, TERF2IP, ACD, and TERT, respectively." (PMID 36876055, 2023).
melanoma (continued). "Different from other melanoma subtypes, TERT alterations are rare in uveal melanomas." (PMID 37239381, 2023). "Ragnum hypoxia scores in melanoma patients (SKCM, Wilcoxon p = 0.024) and Buffa scores across entities (PCAWG, Wilcoxon p = 4.678e-21) were higher in samples carrying a TERT promoter mutation." (PMID 37418389, 2023). "In contrast to lung metastasis, in brain metastases of melanoma, besides TERT, amplifications of HGF (hepatocyte growth factor) and MET genes have been found, indicating the presence of a possible autocrine loop of signaling, offering a potential target therapy option for this type of metastasis." (PMID 35628196, 2022). "The gene expression profile pigmented lesion assay (PLA) is a noninvasive tape-stripping test based on the expression of three genes (LINC00518, PRAME, and TERT) in the stratum corneum, intended to inform whether a cutaneous lesion is concerning for melanoma." (PMID 36579219, 2022). "Ex vivo transfection of mRNA-loaded dendritic cell vaccines against a variety of tumor specific antigens such as telomerase reverse transcriptase (TERT) and the melanoma cell line B16F10 have led to generation of a strong antitumor immune response in murine melanoma models." (PMID 36016150, 2022). "In this review, we describe the latest advances in the role of TERT promoter mutations and telomerase in promoting the occurrence, development, and poor prognosis of melanoma and discuss the clinical significance of the TERT promoter and telomerase in the treatment of melanoma." (PMID 35903534, 2022). "A previous study found TERT T349C to be present in 52% of melanoma cell lines." (PMID 35494035, 2022). "The most frequent TERT SNP (T349C; rs2853669) was found in 76% of our melanoma cohort." (PMID 35494035, 2022). "Finally, additional molecular oncogenic alterations, including alterations in CDKN2A, TERT, and other genes, cause DPN-like melanoma." (PMID 35336833, 2022). "Altogether, mutations in these genes, associated with CDK4, TERT promoter, and MITF, are found in < 3% of melanoma-prone families in studied populations, and the majority (>70%) of familial cases are of unknown etiology." (PMID 35085295, 2022). "Another Chinese study showed that the incidence of TERT copy number gain in AM (61.5%) was higher than that in other melanoma subtypes, suggesting that TERT inhibition might be a potential therapeutic strategy for AM." (PMID 36125617, 2022). "However, in melanoma cell lines, both TERT transcription and telomerase activity decreased sharply after short-term exposure to MAPK inhibitors, regardless of the TERT promoter mutations." (PMID 35903534, 2022). "Moreover, TERT c.-124C>T has also been found in other solid tumors, such as melanoma and hepatocellular carcinoma, and its presence in cfDNA has been associated with poor prognosis." (PMID 36233035, 2022). "In addition, the positive expression of TERT in primary melanoma is related to the reduced survival rate of single-factor analysis; and in metastatic melanoma, there is also a trend between the positive expression of TERT and the decreased survival rate." (PMID 35903534, 2022). "Third, the presence of TERT promoter mutations are strongly correlated with activating mutations in mitogen-activated protein kinase (MAPK) genes, such as FGFR3, BRAF, and RAS in UCBs, melanoma and TCs, respectively." (PMID 36713366, 2022). "Mutually exclusive somatic TERT promoter mutations, C250T, C228T and CC242TT, were found in 48% (10/21) of the melanoma cohort and increased the overall ctDNA detection rate from 67%, based on detection of driver (NRAS or BRAF) or cancer-associated mutations, to 71%." (PMID 35494035, 2022). "CDKN2A, along with CDK4, TERT, and POT1 genes, are high-risk genes for melanoma." (PMID 35465855, 2022).
melanoma (continued). "On the other hand CYT-low metastatic melanomas had recurrent amplifications in loci 5p15.33 (TERT), 6p25.1 (CDYL), 7p22.2 (RAC1), 12q15 (MDM1) and recurrent deletions in 5q31.2 (CTNNA1, FGF1), 11q22.3 (FDX1, RDX, ZC3H12C), and 15q14 (RASGRP1, CSNK1A1P1, SPRED1)." (PMID 33779796, 2021). "In addition to TERT promoter mutations, BRAFV600E mutation also has an important role in different types of cancer, particularly melanomas and thyroid cancers." (PMID 33483600, 2021). "In our study, CSD melanomas showed a higher prevalence of mutations within the promoter region of TERT, albeit without statistical significance." (PMID 34680367, 2021). "Like Pathway 1 to melanoma, dysplastic nevi are associated with activating mutations of BRAF or NRAS; additional mutation of the TERT promoter and, sometimes, hemizygous loss of CDKN2A are involved in the morphological progression to a “classical” (superficial spreading) melanoma in situ." (PMID 34277420, 2021). "Recent studies of mucosal melanomas by whole exome sequencing demonstrated that mucosal melanomas have a low mutational burden, with frequent structural variants commonly affecting CDK4, MDM2 and TERT." (PMID 34571863, 2021). "Recent preliminary evidence has suggested that alterations in TERT and aberrant telomere lengths might be key mechanisms in pediatric melanomas that need to be validated by large patient cohorts." (PMID 34295326, 2021). "Telomeres in tumors with the TERT promoter mutations are usually shorter than in tumors without those mutations as observed in melanoma and gliomas." (PMID 32409749, 2020). "In the light of these evidences TERT aberrant expression may impact on the establishment of resistance to target therapy in BRAF-mutant melanomas." (PMID 32933538, 2020). "The Guardant360 pan cancer NGS panel (covers 73 genes) developed by Guardant Health has successfully detected TERT promoter mutations in ctDNA from a number of cancers, although melanoma was not included." (PMID 32785074, 2020). "In addition to TERT promoter mutations, a less well-described mutation in the succinate dehydrogenase complex subunit D (SDHD) promoter has been observed in melanoma." (PMID 33024276, 2020). "BRAF and NRAS were also the more frequently mutated genes in melanoma samples as described by others, except the TERT gene which was not included in the NGS panel." (PMID 33083132, 2020). "Specifically, the 42 TERT coding variants found in our dataset were all not-pathogenic variants in melanoma, underlying TERT as a polymorphic gene." (PMID 32850962, 2020). "The prevalence of C228T is higher than C250T in almost all cancer types except melanoma and nonmelanoma skin carcinomas where they have been reported to be equally frequent when compared with total TERT promoter mutated samples." (PMID 32674474, 2020). "Of the utmost interest, we observed that specific TERT promoter mutation c.-124C>T displayed a statistically significant correlation with MAPK inhibitor treatment efficacy, specifically in a subset of BRAFV600 melanoma patients that had poorer PFS and OS." (PMID 32784823, 2020). "The TERT promoter mutations −124 C > T and −146 C > T tend to be mutually exclusive and are reported to account for anywhere from 32% (based on NGS analysis of tissue) to 68–78% (based on ddPCR analysis of tissue) of all melanomas." (PMID 32785074, 2020). "As already highlighted, TERT promoter amplicons did not perform well in our custom melanoma panel, presumably due to the high GC content of around 80%, and we did not detect any TERT promoter mutations in our cohort." (PMID 32785074, 2020).